CTLA4 (cytotoxic T-lymphocyte associated protein 4)
Diseases named in the same sentence as CTLA4 in open-access papers (continued):
Sharing a sentence is not in itself a finding about the gene and the disease.
cancer (continued). "Previous studies have reported the existence of CTLA4 60G/A and CTLA4 -1661A/G polymorphism in cancers." (PMID 24376736, 2013). "The effect of the CTLA-4 -1661A/G polymorphism on cancer susceptibility especially exists in Asians and population based subjects." (PMID 24376736, 2013). "While CTLA-4 blockade has been shown to have powerful anti-cancer effects in some patients, it has also been associated with a significant risk of autoimmune toxicity." (PMID 23557194, 2013). "The effect of the CTLA-4 -1661A/G polymorphism on cancer especially exists in Asians and population based subjects." (PMID 24376736, 2013). "The results on all 13 studies showed that the CTLA-4 -1661A/G polymorphism was significantly associated with an increased cancer risk (GA vs. AA: OR = 1.44, 95%CI = 1.13–1.82; GA+GG vs. AA: OR = 1.35, 95%CI = 1.07–1.69; G vs. A: OR = 1.21, 95%CI = 1.01–1.47)." (PMID 24376736, 2013). "Pooled odds ratios (ORs) and corresponding 95% confidence intervals (CIs) for the relationship between CTLA4 gene polymorphisms and cancer susceptibility were calculated by stata 11 software." (PMID 24376736, 2013). "Firstly, we conducted meta-analysis of the effect of CTLA-4 60G/A polymorphism on the susceptibility of cancers based on 18 case-control studies." (PMID 24376736, 2013). "Interruption of immune regulatory pathways via activation of 4-1BB or cytotoxic T-lymphocyte-associated antigen-4 (CTLA-4) blockade appears to be a promising strategy for cancer immunotherapy." (PMID 22312406, 2012). "Monoclonal antibodies specific for cytotoxic T lymphocyte-associated antigen 4 (anti-CTLA4) are a novel form of cancer immunotherapy." (PMID 21779410, 2011). "SNPs in CTLA4 have been reported to be associated with susceptibility to both autoimmune disease and cancer." (PMID 23554684, 2011). "In molecular epidemiological studies, CTLA4 G49A was found to be significantly associated with risk of multiple types of cancer." (PMID 23554684, 2011). "Compared with the common CTLA-4 +49G > A GG genotype, the carriers of variant genotypes (CTLA-4 +49 GC/CC) had a 1.24-fold elevated risk of cancer (95% CI = 1.18-1.32, P < 0.05) under the dominant genetic model, as estimated using a fixed effect model." (PMID 20920330, 2010). "We searched NCBI PubMed using the key terms 'CTLA-4' 'cancer' and 'polymorphism' and found 36 epidemiological studies." (PMID 20920330, 2010). "We preformed a meta-analysis using 22 eligible case-control studies (including 32 datasets) with a total of 11,273 patients and 13,179 controls to summarize the existing data on the association between the CTLA-4 +49G > A polymorphism and cancer risk." (PMID 20920330, 2010). "The associations between the CTLA-4 +49G > A genotype and cancer risks were estimated using dominant (GA+AA vs GG) genetic models in either fixed or random effect models according to the heterogeneity Q test." (PMID 20920330, 2010). "The CTLA-4 +49G > A polymorphism is one of the most commonly studied polymorphisms in this gene due to its association with cancer risks, but previous results have been conflicting." (PMID 20920330, 2010). "Recent studies have shown that polymorphisms in the inhibitory molecule CTLA-4 alter cancer susceptibility through modification of T-cell response." (PMID 21127709, 2010). "So in order to summarize and clarify the published data we have performed a meta-analysis, using all eligible case-control studies to assess the association between the CTLA-4 +49 A > G polymorphism and cancer risk." (PMID 20920330, 2010). "CTLA-4 deficiency induces senescence via the DNA PKcs-STING-AKT pathway in cancer cells." (PMID 41639053, 2026). "Targeting programmed cell death protein 1 (PD-1) and cytotoxic T-lymphocyte-associated protein 4 (CTLA-4) with immune checkpoint inhibitors (ICIs) has improved survival across multiple cancer types, but the variability in patient response highlights the need for better predictive biomarkers." (PMID 42026803, 2026).
cancer (continued). "The development of T cell immune-checkpoint inhibitors (ICI) such as antibodies blocking the programmed cell death protein 1 (PD1) or its ligand (PD-L1) and the cytotoxic T-lymphocyte-associated antigen 4 (CTLA-4), has rapidly introduced immunotherapy for clinical management of several cancer types." (PMID 40124507, 2025). "The benefits of immunotherapy in the treatment of cancer are suggested by the clinical success of blocking antibodies that target p programmed cell death-1 (PD-1) and cytotoxic T lymphocyte-associated antigen-4 (CTLA-4)." (PMID 40230883, 2025). "Cancer cells can evade immune destruction by enhancing expression of immune checkpoints, including programmed cell death protein-1 (PD-1) and cytotoxic T-lymphocyte-associated protein 4 (CTLA-4)." (PMID 40183896, 2025). "The targets of ICIs approved for cancer treatment are PD-1/programmed death ligand 1 (PD-L1), cytotoxic T-lymphocyte associated protein 4 (CTLA-4), and lymphocyte activation gene-3 (LAG-3), and XPO1 inhibition has been shown to modulate the expression of these molecules." (PMID 40291981, 2025). "Among these strategies, immune checkpoint blockade (ICB), specifically targeting the programmed cell death protein 1/programmed death-ligand 1 (PD-1/PD-L1) axis and cytotoxic T-lymphocyte-associated protein 4 (CTLA-4), stands as a cornerstone of contemporary cancer immunotherapy." (PMID 41322140, 2025). "Immune checkpoint inhibitor (ICI) therapy uses monoclonal antibodies to boost the anti-cancer immune response by targeting the major immune checkpoint molecules: programmed cell death protein 1 (PD-1) and its ligand PD-L1 and cytotoxic T-lymphocyte-associated protein 4 (CTLA-4)." (PMID 40075580, 2025). "Cancer treatment in the last decade has hugely been the introduction of T cell-targeted immunomodulators blocking the immune checkpoints Cytotoxic T-Lymphocyte-Associated Protein 4 (CTLA-4), programmed cell death protein 1 (PD1) and PDL1." (PMID 40277760, 2025). "Immune checkpoint inhibitors have revolutionised cancer immunotherapy and agents targeting programmed cell death protein-1 (PD-1), programmed death-ligand 1 (PD-L1) and cytotoxic T-lymphocyte associated protein-4 (CTLA-4) are approved for use in many solid tumour types." (PMID 41154376, 2025). "Indeed, immune checkpoint inhibitors targeting programmed death (PD1) and cytotoxic T-lymphocyte-associated protein 4 (CTLA4) have been used in the treatment of several malignancies." (PMID 41007347, 2025). "Immune checkpoint inhibitor (ICI) therapy represents a ground-breaking paradigm in cancer treatment, harnessing the immune system to combat malignancies by targeting checkpoints such as cytotoxic T-lymphocyte-associated protein 4 (CTLA-4) and programmed cell death protein 1 (PD-1)." (PMID 39039301, 2025). "Immune checkpoint blockade (ICB) therapy, targeting programmed cell death ligand‐1 (PD‐L1)/programmed cell death protein 1 (PD‐1) axis and cytotoxic T‐lymphocyte‐associated protein 4 (CTLA‐4), has exhibited amazing clinical outcomes in various types of cancers." (PMID 39912421, 2025). "Both Long COVID and cancer are associated with profound alterations in immune cell function, including T cell exhaustion, increased expression of immune checkpoint molecules (PD-1, CTLA-4), and impaired antigen presentation." (PMID 41262872, 2025). "ICIs block key interactions between cancer cells and checkpoint molecules such as cytotoxic T-lymphocyte-associated protein 4 (CTLA-4, e.g., ipilimumab), programmed cell death 1 (PD-1, e.g., nivolumab), and programmed cell death ligand 1 (PD-L1, e.g., atezolizumab)." (PMID 41304963, 2025). "In cancer immunology research, IC molecules have garnered marked attention, particularly T cell-associated IC molecules such as programmed cell death ligand-1 (PD-L1) and cytotoxic T lymphocyte-associated protein 4 (CTLA-4), among others." (PMID 40463500, 2025).
cancer (continued). "Immune checkpoint blockade (ICB) has demonstrated promise in patients with malignant tumors, particularly antibodies targeting programmed cell death-1 (PD-1) and cytotoxic T-lymphocyte-associated protein-4 (CTLA-4), has demonstrated promise as a representative immunotherapy." (PMID 40933890, 2025). "CTLA4 has been linked to deficient T cell responses in cancer, but its role in fibrotic disorders remains unclear." (PMID 40100323, 2025). "Exhausted T cells exhibit reduced cytokine production, limited proliferative capacity, and high expression of inhibitory receptors like programmed cell death 1 (PD-1) and cytotoxic T-lymphocyte-associated antigen 4 (CTLA-4), all of which impair their ability to attack cancer cells effectively." (PMID 40406147, 2025). "In the cancer world, the development of immune checkpoint inhibitors that target molecules, such as programmed cell death protein-1 (PD-1), its ligand, PD-L1, and Cytotoxic T-lymphocyte-associated protein-4 (CTLA-4), have revolutionized the treatment of many cancer types." (PMID 40227644, 2025). "Checkpoint inhibition (e.g., PD-1/PD-L1 and CTLA-4 blockade) has demonstrated efficacy in human papillomavirus (HPV)-associated cancers and may be adapted for veterinary applications." (PMID 41157593, 2025). "One of the most exploited mechanisms by tumors involves immune checkpoints, such as PD-L1 (programmed death-ligand 1) and CTLA-4 (cytotoxic T-lymphocyte associated protein 4), which inhibit T-cell activation, allowing cancer cells to escape immune-mediated destruction." (PMID 41031324, 2025). "In recent years, immune checkpoint inhibitors (ICIs), especially monoclonal antibody targeting immune checkpoints such as programmed cell death protein 1 (PD-1), programmed death-ligand 1 (PD-L1) and cytotoxic T-lymphocyte-associated protein 4 (CTLA-4) have transformed the treatment of many cancers." (PMID 40231233, 2025). "T-cell-mediated immune responses against different cancer types are restored by immune checkpoint inhibitors (ICIs), such as monoclonal antibodies that block cytotoxic T-lymphocyte-associated protein 4 (CTLA-4), programmed death 1 (PD-1), or its ligand (PD-L1)." (PMID 41304899, 2025). "Mutations in the CTLA4 gene have been associated with a range of clinical manifestations, encompassing different autoimmune conditions affecting specific organs, hypo-gammaglobulinemia, recurrent infections, and cancer." (PMID 39854591, 2025). "Two such immune checkpoints that have garnered particular interest for cancer immunotherapy treatment are programmed cell death protein 1 (PD-1) and cytotoxic T-lymphocyte-associated antigen 4 (CTLA-4); two highly popular immunological checkpoints are CTLA-4 and CD152, respectively." (PMID 40091960, 2025). "These combination strategies often include cytotoxic T-lymphocyte-associated protein 4 (CTLA-4) blockade, chemotherapy, radiotherapy, or cancer vaccines, which collectively enhance antigen presentation and T cell activation, thereby improving antitumor responses." (PMID 40432108, 2025). "Cancer cells mainly evade surveillance and killing of human immune system by interfering with immune checkpoints including PD-1, programmed cell death ligand-1 (PD-L1), and cytotoxic T lymphocyte-associated antigen-4 (CTLA-4)." (PMID 39923010, 2025). "Notably, inhibitors targeting programmed death 1 (PD-1), programmed cell death ligand 1 (PD-L1), and cytotoxic T-lymphocyte-associated protein 4 (CTLA-4) have been instrumental in managing various cancers." (PMID 40811627, 2025). "ICB therapies enhance the immune system’s ability to fight cancer by targeting immune-regulatory pathways, including programmed cell death protein-1 (PD-1), programmed death-ligand 1 (PD-L1), and cytotoxic T-lymphocyte-associated protein 4 (CTLA-4)." (PMID 40332249, 2025).
cancer (continued). "As a landmark advancement in cancer therapeutics, ICIs restore T-cell antitumor activity by obstructing signaling pathways, notably programmed cell death protein 1/programmed death-ligand 1 (PD-1/PD-L1) and cytotoxic T-lymphocyte-associated protein 4 (CTLA-4)." (PMID 41425710, 2025). "Some studies have demonstrated that in TSC2-mutated cancer both combination therapy with PD-1 and CTLA-4 antibodies, as well as monotherapy, can enhance CD8+ T cell infiltration in TSC2-deficient human tumors, with the level of infiltration correlating with treatment response." (PMID 40994638, 2025). "This research highlights how CTLA-4 SNPs may impact both cancer susceptibility and immune system activity." (PMID 41244914, 2025). "Additionally, the immunosenescence pathways associated with immune exhaustion (e.g., PD-1, CTLA-4, cellular senescence) and pathways in cancer were also upregulated." (PMID 39941028, 2025). "Moreover, cancer cells are able to elevate the level of immune checkpoint molecules such as Cytotoxic T-lymphocyte associated protein 4 (CTLA-4) and programmed death-ligand 1 (PD-1), which help them suppress the immune response." (PMID 40650799, 2025). "In addition, we found that PDCD1 and CTLA4 were also associated with PTBP1 expression in these 3 cancer types." (PMID 38918441, 2024). "Despite being antigenic and evoking immune responses, cancer can escape destruction through a variety of mechanisms including upregulation of immune checkpoints such as programmed death-1 (PD-1) and cytotoxic T-lymphocyte-associated antigen 4 (CTLA-4)." (PMID 38183112, 2024). "Applications of immune checkpoint inhibitors (ICIs), especially those targeting CTLA-4 (cytotoxic T-lymphocyte associated protein 4) and PD-1/PD-L1 (programmed cell death protein 1/programmed cell death ligand 1), have revolutionized the treatment of various aggressive cancers." (PMID 38475836, 2024). "Immune checkpoint inhibitors (ICIs) are monoclonal antibodies that have revolutionized the treatment landscape of various cancers by targeting cytotoxic T-lymphocyte-associated antigen-4 (CTLA-4), programmed cell death protein-1 (PD-1), and programmed death-ligand 1 (PD-L1)." (PMID 40729268, 2024). "The development and approval of immune checkpoint (programmed cell death protein 1 [PD-1], programmed cell death-ligand 1 [PD-L1], and cytotoxic T-lymphocyte associated protein 4 [CTLA4]) inhibitors leaded to dramatic changes in the landscape of cancer therapy." (PMID 39351094, 2024). "In this study, we used strain-resolved metagenomic classification to discover a signature of 22 gut microbial strains associated with response to combination ipilimumab (anti-CTLA-4) plus nivolumab (anti-PD-1) in a phase 2 trial cohort of Australian patients with diverse rare cancers (n = 106)." (PMID 38429524, 2024). "Immune checkpoint inhibitors (ICIs) such as PD1 (e.g., nivolumab or pembrolizumab), programmed death-protein-ligand PD-L1 (e.g., durvalumab), or cytotoxic T lymphocyte-associated protein 4 CTLA-4 (e.g., ipilimumab) inhibitors have dramatically improved prognosis of cancers and are widely used." (PMID 38807591, 2024). "Secondly, immune checkpoint molecules, such as PD-L1 and cytotoxic T-lymphocyte associated protein 4(CTLA4), have been extensively investigated as a cancer therapy, with this immunotherapy notably enhancing the survival rates of patients with certain types of cancer." (PMID 39845945, 2024). "Similarly to the PD-1 pathway, the overexpression of CTLA-4 is a hallmark of T-cell exhaustion, as it occurs during chronic infections and in the cancer microenvironment, resulting in a dampening of the immune system." (PMID 39001436, 2024). "The use of genetically engineered chimeric antigen receptor (CAR) T cells and immune checkpoint inhibitors (ICI) targeting cytotoxic T-lymphocyte associated protein 4 (CTLA4) or programmed death 1 (PD1)/programmed death-ligand 1 (PD-L1) axis has drastically improved survival in several cancer types." (PMID 39408714, 2024).
cancer (continued). "Among these therapies, immune checkpoint inhibitors (ICIs) are a form of targeted therapy that disrupt the immune evasion mechanisms of cancer cells by inhibiting cytotoxic T lymphocyte-associated antigen 4 (CTLA-4) and the programmed cell death protein 1 pathway (PD-1/PD-L1)." (PMID 39459421, 2024). "In Cancer immunotherapy, mAbs can be used as checkpoint inhibitors for example programmed cell death 1 ligand 1 (PD-L1) antibody and cytotoxic T lymphocyte-associated antigen 4 (CTLA-4)." (PMID 39390211, 2024). "Notably, ICIs targeting PD‐1 (programmed cell death protein 1), PD‐L1 (programmed death‐ligand 1), and CTLA‐4 (cytotoxic T‐lymphocyte‐associated protein 4) in conjunction with personalized cancer vaccines has shown promising results." (PMID 39399642, 2024). "By inhibiting immunological checkpoints like cytotoxic T-lymphocyte-associated protein 4 (CTLA-4) and programmed cell death protein 1 (PD-1), these blockers activate the cytotoxic function of T-cells targeting cancer cells, resulting in long-lasting and effective responses in certain patients." (PMID 39127974, 2024). "There is evidence suggesting that BRAF and MEK inhibition induces CD4 and CD8 T lymphocytes, boosting their cytotoxicity against cancer cells, which is evident by elevated granzyme B and perforin levels, and an elevated expression of cytotoxic T-lymphocyte-associated protein-4 (CTLA-4)." (PMID 38731852, 2024). "This hypothesis is consistent with observations in animals treated with anti–CTLA-4 in the setting of cancer, wherein studies showed that changes in intestinal microbiota altered susceptibility to anti–CTLA-4 checkpoint inhibition." (PMID 38226924, 2024). "In addition, ALDH1A2, CARD11 and CTLA4 are implicated in cancer immunity and can be useful prognostic biomarkers in some cancer types." (PMID 39351147, 2024). "However, only a small portion of patients with cancer achieve positive responses to ICIs, mainly, to inhibitors of PD-1 (programmed cell death protein 1), PD-L1 (programmed death-ligand 1), and CTLA-4 (cytotoxic T-lymphocyte-associated protein 4)." (PMID 38540157, 2024). "Furthermore, persistent CTLA-4 expression has been linked to susceptibility to various solid tumors, with differing expression levels potentially influencing cancer progression and clinical outcomes." (PMID 38473398, 2024). "Immune checkpoint inhibitors (ICIs), including cytotoxic T-lymphocyte-associated protein 4 (CTLA-4) and programmed cell death protein 1 (PD-1) inhibitors, are also gaining traction for their potential to enhance the immune system’s response against cancer." (PMID 39200270, 2024). "Notably, the use of anti-CTLA-4 monoclonal antibodies in cancer treatment is associated with the development of granulomatous disease." (PMID 39062076, 2024). "Collectively, the PD-1/PD-L1 and CTLA-4, which are commonly employed in cancer immunotherapy, exhibited notable distinctions between the three clusters, suggesting that the expression patterns of lncRNAs were associated with the immune checkpoints in cancer." (PMID 39126025, 2024). "In addition, our results highlight the prominent role of other surface receptors of CTLs and NK cells, such as TIGIT and CTLA-4, as actionable co-inhibitory signals beyond PD-1 in advanced/high-risk cSCCs enriched in hybrid E/M and mesenchymal cancer cells." (PMID 38914547, 2024). "For instance, cancer cells directly suppress T-cell responses by binding to adaptive immune checkpoints such as programmed death 1 (PD-1) and cytotoxic T-lymphocyte-associated antigen 4 (CTLA-4)." (PMID 39135069, 2024).